IQSEC1 (IQ motif and Sec7 domain ArfGEF 1)
Description:
Guanine nucleotide exchange factor for ARF1 and ARF6. Guanine nucleotide exchange factor activity is enhanced by lipid binding. Accelerates GTP binding by ARFs of all three classes. Guanine nucleotide exchange protein for ARF6, mediating internalization of beta-1 integrin. Involved in neuronal development (Probable). In neurons, plays a role in the control of vesicle formation by endocytoc cargo. Upon long term depression, interacts with GRIA2 and mediates the activation of ARF6 to internalize synaptic AMPAR receptors (By similarity).
Synonyms: BRAG2; ARFGEP100; KIAA0763; GEP100; ARF-GEP100; IDDSSBA
Tractability: Small molecule: a structure with a bound ligand is known. PROTAC: ubiquitination databases record sites on it; its protein half-life has been measured.
Gene: Protein-coding gene on chromosome 3 (12,897,043 to 13,283,281, reverse strand). Ensembl gene ENSG00000144711.
Subcellular location: Cytoplasm; Nucleus; Postsynaptic density; Cytoplasmic vesicle, secretory vesicle, synaptic vesicle
Subcellular location (Human Protein Atlas): Cytosol; Centrosome; Nucleoplasm; Vesicles
Gene Ontology:
Molecular function: guanyl-nucleotide exchange factor activity; protein binding; protein kinase binding
Biological process: regulation of focal adhesion assembly; dendritic spine development; positive regulation of focal adhesion disassembly; positive regulation of keratinocyte migration; regulation of postsynaptic neurotransmitter receptor internalization; postsynaptic modulation of chemical synaptic transmission; regulation of ARF protein signal transduction
Cellular component: cytoplasm; cytosol; endoplasmic reticulum-plasma membrane contact site; membrane; nucleoplasm; nucleus; postsynaptic density; postsynaptic density membrane; glutamatergic synapse; postsynaptic density, intracellular component; Schaffer collateral - CA1 synapse; synaptic vesicle
Genetic constraint (gnomAD): Loss-of-function variants: 30 observed, 86.3 expected, observed/expected ratio (o/e) 0.35, 90% interval 0.26 to 0.47. The upper end of that interval is the gene's LOEUF score, 0.47, which puts it in group 2 of 6, group 1 being the genes least tolerant of losing a copy. Missense variants: 1,387 observed, 1,562.2 expected, observed/expected ratio (o/e) 0.89, 90% interval 0.85 to 0.93. Synonymous variants: 697 observed, 659.09 expected, observed/expected ratio (o/e) 1.06, 90% interval 0.99 to 1.13.
Homologues: Orthologues: chimpanzee IQSEC1 (99% identical), macaque IQSEC1 (99% identical), dog IQSEC1 (94% identical), mouse Iqsec1 (92% identical), rat Iqsec1 (92% identical), pig IQSEC1 (92% identical), guinea pig IQSEC1 (91% identical), rabbit IQSEC1 (84% identical), tropical clawed frog iqsec1 (80% identical), zebrafish iqsec1b (80% identical), zebrafish IQSEC1 (63% identical), Drosophila melanogaster siz (35% identical), and 5 more. Paralogues in human: IQSEC2 (58% identical), IQSEC3 (38% identical), ARFGEF2 (19% identical), ARFGEF1 (18% identical), GBF1 (18% identical), MON2 (16% identical), PSD3 (14% identical), PSD (13% identical), PSD2 (13% identical), PSD4 (13% identical), CYTH3 (12% identical), CYTH1 (12% identical), and 3 more.
Diseases named in the same sentence as IQSEC1 in open-access papers:
IQSEC1 is named in the same sentence as 42 diseases in open-access papers, as found by Europe PMC text mining. Sharing a sentence is not in itself a finding about the gene and the disease. The quoted sentences say what the papers report.
breast carcinoma (20 papers, 2009 to 2023). "Because previous reports have linked IQSec1 to metastatic breast cancer, here we focused on the highly metastatic breast cancer cell line, MDA-MB-231." (PMID 32234213, 2020). "IQSEC1 links epidermal growth factor receptor signaling to ARF6 activation to induce breast cancer invasion." (PMID 23202957, 2012).
Intellectual disability (3 papers, 2020 to 2024). "Mutations of IQSEC1 were found to be associated with intellectual disability, Alzheimer’s disease, and attention-deficit/hyperactivity disorder." (PMID 37246165, 2023). "A mutation in IQSEC1 can cause intellectual disability, developmental delay, and short stature." (PMID 31940795, 2020).
epilepsy (2 papers, 2023 to 2025). A brain disorder characterized by episodes of abnormally increased neuronal discharge resulting in transient episodes of sensory or motor neurological dysfunction, or psychic dysfunction. "These two epilepsy-susceptibility genes identified by PWAS were IQSEC1 (IQ motif and Sec7 Domain ArfGEF 1, chromosome 3), and JAM2 (junctional adhesion molecule 2, chromosome 21)." (PMID 37246165, 2023). "We identified five significant genes (WIPF1, IQSEC1, JAM2, ICAM3, and ZNF143) that had causal relationships with epilepsy." (PMID 37246165, 2023). "However, the potential role of IQSEC1 in epilepsy has not been identified." (PMID 37246165, 2023).
metastatic cancer (2 papers, 2021). A carcinoma which has spread from the original site of growth to another anatomic site. "We also identified six genes (KHDRBS2, IQSEC1, ARHGEF1, ARID5A, IRX5, and TMC6) that were activated in metastatic cancers in two of the three cancer types and might be associated with metastatic traits." (PMID 34294701, 2021).
prostate carcinoma (2 papers, 2021 to 2023). A carcinoma that arises from epithelial cells of the prostate gland. "Western blotting of androgen receptor (AR)-proficient and -deficient prostate lines confirmed upregulation of ARF6 and IQSEC1 protein expression in metastatic prostate cancer cell lines (LNCaP, VCaP, DU145, PC3)." (PMID 33712589, 2021). "We reported a similar function of ARF6 regulating protrusion maturation rather than initiation in conjunction with the ARF GEF protein IQSEC1 in invading 3D cultures of prostate cancer cells (PC3)." (PMID 37577760, 2023). "IQSEC1 allowed robust stratification of prostate cancer patients, stratifying a 24-month decrease in median overall survival in IQSEC1-elevated patients (665 patients)." (PMID 33712589, 2021). "We tested the generalisability of IQSEC1 inhibition to inhibit growth and invasion mechanisms in commonly used prostate cancer models." (PMID 33712589, 2021). "Elevation in IQSEC1, ARF5 and ARF6 levels was associated with clinical outcome in prostate cancer across 12 studies, representing 2910 patients." (PMID 33712589, 2021). "We examined the association of IQSEC1, ARF5, and ARF6 elevation with frequent genomic alterations in prostate cancer." (PMID 33712589, 2021).
Bethlem myopathy 1 (1 paper, 2023). "This was, for instance, the case for COL6A1, associated with Bethlem myopathy 1 (OMIM #158810) and Ullrich congenital muscular dystrophy 1 (OMIM #254090), and for IQSEC1, associated with severe ID (OMIM #618687)." (PMID 38137073, 2023).
depression (1 paper, 2023). "The most significant CpG (cg01601845; p = 1.53 × 10–6) was located in Open Sea in the gene-body of the IQSEC1 gene, gene linked to regulation of postsynaptic neurotransmitter receptor internalization, as well as to treatment response in depression with citalopram in a prior GWAS (rs11128623)." (PMID 37664245, 2023).
Epileptic encephalopathy (1 paper, 2024). A condition in which epileptiform abnormalities are believed to contribute to the progressive disturbance in cerebral function. "The IQSEC1 and IQSEC2 proteins are Ca+/CaM-regulated synaptic proteins that can activate all members of the ARF GTPase family and are mutated in neuronal developmental disorders including X-linked intellectual disability with early onset epileptic encephalopathy." (PMID 38072052, 2024).
fibrosarcoma (1 paper, 2020). A malignant mesenchymal fibroblastic neoplasm affecting the soft tissue and bone. "A similar increase in adhesion size was also observed upon IQSec1 depletion in the invasive fibrosarcoma cell line HT1080." (PMID 32234213, 2020).
mood disorder (1 paper, 2023). A cognitive disorder a disturbance in which the person's mood is hypothesized to be the main underlying feature. "The most significant gene from the analysis comparing responders and non-responders, IQSEC1, has been linked to treatment response to antidepressant medication at the genetic level, as well as to high-risk individuals prone to developing mood disorders in a DNA methylation study." (PMID 37664245, 2023).
ovarian carcinoma (1 paper, 2012). A malignant neoplasm originating from the surface ovarian epithelium. "A set of eight biomarkers: NKIRAS1/RPL15, THRB, RBPS3 (CTDSPL), IQSEC1, NBEAL2, ZIC4, LOC285205 and FOXP1, was identified as the most prominent set capable to detect both early and late stages of ovarian cancer." (PMID 23202957, 2012).
prostate tumours (1 paper, 2021). "Primary prostate tumours with elevated IQSEC1 were of significantly higher grade, were associated with tumour-bearing lymph node positivity and metastases." (PMID 33712589, 2021).
renal fibrosis (1 paper, 2022). A final common manifestation of a wide variety of chronic kidney diseases characterized by glomerulosclerosis and tubulointerstitial fibrosis. "Nephronophthisis 4 (NPHP4), transcription factor 3 (TCF3), and IQ motif and Sec7 domain 1 (IQSEC1) were found to be involved in pathways that promote the epithelial to mesenchymal transition and renal fibrosis." (PMID 35806113, 2022).
Renal insufficiency (1 paper, 2021). A reduction in the level of performance of the kidneys in areas of function comprising the concentration of urine, removal of wastes, the maintenance of electrolyte balance, homeostasis of blood pressure, and calcium metabolism. "A Renal Insufficiency Cohort (CRIC) identifies enhanced DNA methylation in genes of IQ motif and Sec7 domain 1 (IQSEC1), nephronophthisis 4 (NPHP4), and transcription factor 3 (TCF3) in participants with stable renal function while compared to those with rapid loss of eGFR." (PMID 33737884, 2021).
sarcoma (1 paper, 2021). A usually aggressive malignant neoplasm of the soft tissue or bone. "Analysis of the pan-cancer TCGA dataset for tumour types with profiled normal tissue revealed that four tumour types (kidney, KICH; liver, LIHC; prostate; sarcoma, SARC) displayed IQSEC1 mRNA higher than normal tissue." (PMID 33712589, 2021).
cancer (14 papers, 2009 to 2022). A tumor composed of atypical neoplastic, often pleomorphic cells that invade other tissues. "Finally, we examined the association of IQSEC1 mRNA levels across the pan-cancer TCGA dataset with common tumour-associated signalling pathways from reverse phase protein array (RPPA) data." (PMID 33712589, 2021). "Together, these data indicate a role for tumour-associated isoform switching to IQSEC1 v2 to promote PI3K-AKT signalling and metastasis across cancer types, resulting in treatment resistance and a robust decrease in patient survival." (PMID 33712589, 2021). "Chemical inhibition (NAV-2729) or genetic depletion of IQSEC1 attenuated growth and/or invasion in a range of 3D cancer cell models." (PMID 33712589, 2021). "Critically, we demonstrate that IQSEC1 inhibition blocks growth and invasion in a multitude of in vitro 3D models across several cancer types, and tumour growth and metastasis in vivo." (PMID 33712589, 2021). "Thus, IQSEC1 is required for growth and invasion across a number of 3D cell models from different cancer types." (PMID 33712589, 2021). "Within each cancer type IQSEC1 expression was divided into high and low using a median split of mRNA levels, and protein differences between each group that consistently and significantly trended in the same direction across a quarter of all cancer types was calculated." (PMID 33712589, 2021). "IQSEC1 (OMIM ∗610166) also referred to as BRAG2 or GEP100, the IQ motif and SEC7 domain containing-protein are involved in a wide range of cellular processes including cancer metastasis, angiogenesis, myoblast fusion and integrin trafficking." (PMID 34177493, 2021). "We selected novel epigenetic markers including NKIRAS1/RPL15, THRB RBPS3 (CTDSPL), IQSEC1, NBEAL2, ZIC4, LOC285205, CGGBP1, EPHB1 and FOXP1 that allowed detection of cancer in ovarian biopsies on all stages with sensitivity equal to (72 ± 11)% and specificity (94 ± 5)%." (PMID 23202957, 2012).
tumor (10 papers, 2009 to 2023). "Here, we describe that specific pro-invasive transcript variants of the ARF GEF IQSEC1 are upregulated in invasive tumours." (PMID 33712589, 2021). "Elevated IQSEC1 expression is associated with clinical metrics of poor outcome: higher-grade tumours, metastasis, treatment resistance, PI3K pathway activation." (PMID 33712589, 2021). "Mirroring IQSEC1 regulation of phosphoinositide signalling in PC3 cells, a clear PI3K-AKT signature was associated with high IQSEC1 levels across ten tumour types." (PMID 33712589, 2021). "This was accompanied by a switch from the non-invasive IQSEC1 v1 isoform, to the pro-invasive IQSEC1 v2 in tumours." (PMID 33712589, 2021). "Comparison of matched normal–tumour tissue from the TCGA prostate cohort (n = 52) showed a significant increase in overall IQSEC1 mRNA in tumours." (PMID 33712589, 2021). "IQSEC1 increase occurred exclusively with androgen deprivation therapy, retained presence of tumour after therapy, and increased levels of the androgen receptor V7 variant, a major mechanism for escape from androgen deprivation." (PMID 33712589, 2021). "It is notable switching to the pro-invasive IQSEC1 v2 occurs in at least a quarter of all sampled tumour types, suggesting this may be a major mechanism underpinning tumourigenesis." (PMID 33712589, 2021). "While IQSEC1 depletion did not significantly attenuate tumour incidence, tumour area and volume were significantly reduced." (PMID 33712589, 2021). "However, seven tumour types showed that rather than an increase in overall IQSEC1, instead tumours underwent an isoform switch from v1-to-v2." (PMID 33712589, 2021).
prostate (1 paper, 2021). "We observed an association of the GEF IQSEC1 (also called BRAG2/GEP10032) with prostate tumorigenesis." (PMID 33712589, 2021).
IQSEC1 also shares sentences with these, for which no sentence is quoted: lung adenocarcinoma (3 papers); Alzheimer disease (2); developmental delay (2); hepatoma (2); attention deficit-hyperactivity disorder (1); breast ductal carcinomas (1); childhood apraxia of speech (1); Cognitive impairment (1); head and neck squamous cell carcinoma (1); infection (1); invasive breast carcinoma (1); language delay (1); language disorder (1); Motor delay (1); neurodevelopmental disorder (1); Onset (1); pancreatic cancer (1); pancreatic ductal adenocarcinoma (1); Parkinson disease (1); schizophrenia (1); Seizure (1); triple-negative breast carcinoma (1); Ullrich congenital muscular dystrophy 1 (1); X-linked intellectual disability (1).